PGR (progesterone receptor)
Diseases named in the same sentence as PGR in open-access papers (continued):
Sharing a sentence is not in itself a finding about the gene and the disease.
endometriosis (continued). "Dysregulation of PGR signaling as a part of progesterone resistance has been reported in endometriosis." (PMID 35203298, 2022). "The main therapeutic activity of progestogens in endometriosis is due to progesterone receptor signaling, which induces the downregulation of estrogen receptors." (PMID 35538479, 2022). "ClusterB was demonstrated to be correlated with significantly overexpressed VEGF and notably downregulated ESR1 and PGR, which are convincing biomarkers of endometriosis." (PMID 36672827, 2022). "Meanwhile, progesterone receptor (PGR), which downregulates oestrogen receptors, was decreased in endometriosis FBs." (PMID 34233737, 2021). "Aromatase inhibitors, GnRH antagonists, anti-tumor necrosis factor- α (TNF-α), antiangiogenic factors and selective progesterone receptor modulators are the newest medical therapies for endometriosis." (PMID 33804660, 2021). "In this context, low classical PGR expression in the ectopic endometrium of patients with endometriosis, compared to eutopic tissue, has been reported in the literature, even though studies are equivocal." (PMID 34681937, 2021). "HOXA10, estrogen receptor α, and progesterone receptor are highly expressed in rectosigmoid endometriosis lesions, which are characteristic lesions of DIE." (PMID 34367069, 2021). "The growth of endometriosis is hormone dependent; evidenced by estrogen and progesterone receptor in endometriosis epistle and stromal." (PMID 32345338, 2020). "Recent advances had been made with respect to elucidating partial progestin response based on the progesterone receptor status of endometriosis patients, which infers the prospect of precision or targeted medicine for treating endometriosis." (PMID 32429215, 2020). "This blunted or inadequate response to progesterone in Endometriosis is due to low expression of the progesterone receptor and decrease expression in progesterone target genes." (PMID 33354460, 2020). "Endometriosis is characterized by progesterone resistance, which has been explained in part by a decrease in the expression of the intracellular progesterone receptor in the ectopic endometrium." (PMID 32733932, 2020). "CD 10 immunostaining of the stroma, as well as estrogen and progesterone receptor staining of the glandular component, were both consistent with endometriosis." (PMID 32692401, 2020). "KRAS mutations are more frequent in cases of adenomyosis with co-occurring endometriosis, low progesterone receptor (PR) expression, or progestin (dienogest; DNG) pretreatment." (PMID 31857578, 2019). "When endometrial tissue fails to respond properly to P4 exposure, this is termed P4 resistance, and it manifests itself in endometriosis as failed induction of PGR activation, or P4 target gene transcription in the presence of bioavailable P4." (PMID 31387263, 2019). "In post-menopausal patients with recurrence or new onset of endometriosis with comorbidities contraindicating the surgical approach, progestogens are a reliable strategy, thanks to their direct action on the progesterone receptor of endometrial ectopic tissue." (PMID 31416164, 2019). "The purpose of present study was to compare progestins and selective progesterone receptor modulator as new indication for endometriosis, and the results of the study already showed positive therapeutic effects in clinical dose." (PMID 29615065, 2018). "On the contrary, the progesterone receptor is highly expressed in endometrial cells and used as target of current therapeutic interventions for endometriosis that use progesterone analogues to block ER activity." (PMID 28317921, 2017). "A baboon model of endometriosis induced by unopposed estrogenicity using progesterone receptor antagonist (EC304) was used in this study." (PMID 26908459, 2016). "Recently selective progesterone receptor modulators (SPRMs or mesoprogestins) have been proven to be very useful in the treatment of endometriosis." (PMID 26908459, 2016).
endometriosis (continued). "One remarkable finding from this analysis was that it correctly identified the HOXA cluster, NR5A1, and PGR—genes that are aberrantly methylated and differentially expressed in endometriosis—as highly significant." (PMID 24603652, 2014). "Selective progesterone receptor modulators, such as Asoprinil, are now under investigation in the treatment of uterine fibroids and endometriosis." (PMID 24401087, 2014). "Recent evidence demonstrates altered PGR expression in the endometrium of endometriosis patients." (PMID 40072055, 2025). "Our study indicates that PFAS may regulate the expression of oxidative stress-related genes, such as NR3C1 and PGR, disrupting the normal function of endometrial cells and promoting the development of endometriosis." (PMID 41492385, 2025). "In addition, estrogen receptor 1 (ESR-1) levels are higher in the midsecretory phase endometrium of women with endometriosis-related infertility than in control subjects, although progesterone receptor expression levels are lower in these subjects." (PMID 38276248, 2024). "GnRH antagonists, selective estrogen receptor modulators (SERMs), and selective progesterone receptor modulators (SPRMs) have shown potential in alleviating endometriosis-related symptoms while minimizing the systemic side effects associated with hormonal therapies." (PMID 39065678, 2024). "Clinical benefits in the treatment of endometriosis and uterine myoma with the suppression of GnRH and the use of selective progesterone receptor modulators allow us to suggest that approaches that are not based on complete suppression of the GnRH axis have clear clinical significance." (PMID 38255200, 2024). "The mechanism of the shorter menstrual cycles is not known, but it may be hypothesized that luteal progesterone may play a role given that there is evidence of progesterone-receptor resistance in the endometrium of patients with endometriosis." (PMID 37763632, 2023). "The reversal of progesterone resistance, such as re-establishing PGR expression, could inhibit cellular growth and stimulate shedding, thereby providing a novel therapeutic regimen for women with endometriosis." (PMID 37108154, 2023). "The overexpression of miR-196a in the eutopic endometrium inhibited the expression of the progesterone receptor and progesterone receptor B. Additionally, miR-196a upregulates MEK/ERK signaling by downregulating PGR expression in the eutopic endometrium of women with minimal or mild endometriosis." (PMID 36143357, 2022). "Because ablation of Arid1a disrupts PGR signaling and ARID1A can directly bind to PRA, ARID1A is essential for normal endometrial functions and reduced ARID1A expression can alter PGR signaling leading to progesterone resistance in the endometrium with endometriosis." (PMID 35203298, 2022). "Abnormal PGR expression is closely relevant with unexplained infertility and endometriosis (EMS)." (PMID 35244538, 2022). "In eutopic endometrium from women with endometriosis, mir-194-3p could repress the progesterone receptor and decidualization." (PMID 32850438, 2020). "However, since FOXO1 is also regulated by PGR, it is difficult to conclude which molecule becomes dysregulated first in endometriosis based on the current literature." (PMID 31387263, 2019). "Further confirming the comprehensive disruption of P4 signaling in endometriosis, HOXA10, IGFBP1, PLZF, MIG-6, and CRISPLD2, all PGR targets implicated in endometrial function based on mouse studies, have been shown to be dysregulated in endometriosis patients." (PMID 31387263, 2019). "Similarly, progesterone receptor (PGR) was over-expressed in endometriosis eutopic tissue (ES/CS = 1.45, ES/PS = 1.76, EP/CP = 2.42), whilst decreased in ectopic tissue (EcS/ES = 0.32)." (PMID 30992697, 2019).
endometriosis (continued). "Additionally, a loss of progesterone receptivity and signaling vis-à-vis the suppression of progesterone receptor (PGR) activity in the endometrium and in ectopic lesions has been reported to be associated with endometriosis." (PMID 31878927, 2019). "Though dysregulation of PGR target genes displays the consequences of P4 resistance in endometriosis, dysregulation of PGR signaling regulators may help explain the cause of P4 resistance." (PMID 31387263, 2019). "In addition to aberrant production of sex-hormones, the aberrant expression and signalling of the progesterone receptor (PR) has been demonstrated in women with endometriosis." (PMID 27740937, 2017). "Interestingly, CRISPLD2 is regulated by progesterone (P4) and its receptor (PGR) in the uterus, its expression is high during decidualization, constitutive during pregnancy and is dysregulated in patients with endometriosis." (PMID 29100496, 2017). "The observed bleeding irregularities may be due to the effect of progesterone treatment, as noted in women who use progestin-alone contraception or are undergoing treatment for endometriosis using pure progesterone receptor agonists." (PMID 26908459, 2016). "Therefore, understanding the role of the progesterone receptor and its target genes is important for successful therapies in endometriosis." (PMID 24955763, 2014). "Furthermore, there is evidence of a significant correlation between polymorphism of the progesterone receptor gene (PROGINS) and endometriosis." (PMID 23843796, 2013). "Guo on the contrary, reviewing 12 association studies on 5 genes (CYP17, CYP19, Androgen Receptor, Progesterone Receptor, and Estrogen Receptor) found no functional data that support a putative relationship of these genetic polymorphisms with endometriosis." (PMID 23843796, 2013). "In endometriosis patients, defects in the progesterone receptor have been postulated." (PMID 17118173, 2006). "In addition, other nuclear receptor genes, such as Progesterone Receptor (PGR OMIM 607311) and Peroxisome Proliferative Activated Receptor, Gamma (PPARG OMIM 601487) gene have been associated with endometriosis in other case-control studies." (PMID 16131398, 2005). "Although it is premature to conclude unequivocally as of now, we can, at least, suggest that some ER + and PGR + residual cells of neonatal endometria can be reactivated with the onset of thelarche and may culminate in the development of early-onset endometriosis." (PMID 37337237, 2023). "As an alternative mechanism, a significantly less tissue accumulation of immunocompetent cells in neonatal endometria may explain the survival of ER + and PGR + cells should they make entry into the pelvis and consequent development of early endometriosis with the onset of ovarian function." (PMID 37337237, 2023). "However, whether the observed higher expression of PGR observed in eutopic endometrium from endometriosis patients is involved in progesterone resistance, or a response to it, is unclear." (PMID 30992697, 2019). "They revealed that the progesterone receptor directly binds to KLF15, a transcription factor in mid-secretory epithelial endometrial cells, leading to reduced KLF15 expression in endometriosis patients due to progesterone resistance." (PMID 39338174, 2024). "Hormonal treatments for endometriosis primarily target ESR1, ESR2, or PGR and have the highest affinity for these receptors; however, due to the structural similarity of hormone receptors, off-target effects at other receptors are possible." (PMID 37996888, 2023). "The results showed that, compared with normal endometria, the expression of AR, PGR, and PGRMC1 in eutopic endometria derived from patients with endometriosis was decreased." (PMID 36860677, 2023). "Deeper inquiry into endometrial epithelial-stromal crosstalk between ErbB2/ERK/ESR1 and PGR/MIG-6 signaling pathways will be of major importance to understanding infertility and endometriosis." (PMID 35232969, 2022).
endometriosis (continued). "Confirming endometriotic stromal cells in a specimen using immunostaining of ER, PgR, and CD10 is important to diagnose thoracic endometriosis." (PMID 35544515, 2022). "We next analyzed the expression levels of SOX4, PGR, FOXO1, HERC4, IGFBP1, and PRL in the mid-secretory endometrium of healthy women (control, n = 12) versus women who suffered RIF due to endometriosis (EMS-RIF, n = 12)." (PMID 35244538, 2022). "GNRH1, PGR, TNF, CYP19A1, and IL6 were mentioned with the highest frequencies in endometriosis-related articles." (PMID 34917684, 2021). "The ESR1 and PGR expression levels were substantially lower, while the level of ESR2 gene expression was significantly higher in endometriosis than in normal endometrium." (PMID 33153202, 2020). "The results of experimental study, concerning the analysis of ESR1, ESR2, PGR, and CYP19A1 genes, unveil the existence of certain correlations of their expression with endometriosis." (PMID 33153202, 2020). "PGR and ESR1 are also found in the list of the common 39 genes from the three endometriosis-related data sets." (PMID 31879572, 2019). "GnRH antagonists, aromatase inhibitors, selective progesterone receptor modulators, anti-tumor necrosis factor-ɑ (TNF-ɑ), and anti-angiogenic factors are new treatments for endometriosis." (PMID 30402122, 2018). "Finally, hsa-miR-196a is upregulated in eutopic endometrium of women with minimal or mild endometriosis, promoting MEK/ERK signalling, suppressing progesterone receptor expression, and impairing decidualization in endometrial stromal cells." (PMID 41501788, 2026). "However, because of the inherent progesterone resistance of endometriosis lesions and their low progesterone receptor expression, it is difficult to compare the subtypes, and it is still controversial whether there is a difference in progesterone receptor expression in subtypes’ lesions." (PMID 39968688, 2025). "High ROR1 was significantly associated with lack of hormonal treatment and increased Ki67, but not with progesterone receptor status, surgical history, disease stage, Endometriosis Fertility Index, infertility, pain scores, family history, or co-diagnoses." (PMID 41415567, 2025). "Up-regulation of YAP1/miR-21-5p decreases PGR expression and plays a negative role in the development of endometriosis." (PMID 39057685, 2024). "pSTAT3, which interacts with PGR signaling to promote implantation and decidualization, is significantly higher in the endometrium of both women and non-human primates with endometriosis." (PMID 37108154, 2023). "In patients with mild endometriosis, the expression profiles of PGR, CFP1, and P4 target genes are not different from those of the control group." (PMID 37270588, 2023). "Essentially, the activation of PGR downstream pathways with SAG rescued the abnormal epithelial proliferation in Cfp1d/d uterus and suppressed the ectopic growth of Cfp1d/d uterine lesions with P4 resistance in the endometriosis model." (PMID 37270588, 2023). "These DNA methyltransferases were expressed differently in endometriosis, and there may be abnormal methylation of HOXA10 and the progesterone receptor PR-B that affects gene expression." (PMID 36143357, 2022). "The results illustrate that clusterB was correlated with a significantly lower expression of ESR1 and PGR and a higher expression of VEGF, which revealed that the cluster might have a correlation with endometriosis." (PMID 36672827, 2022). "Likewise, upregulation of miR-194-3p in eutopic endometrium inhibited PGR expression and ESC decidualization in endometriosis, which hinders fertility by repressing the levels of PGR and decidualization in the eutopic endometrium." (PMID 32658928, 2020). "Recently selective progesterone-receptor modulators (SPRM) and new generation progestins have been speculated or indicated as potential treatment for endometriosis." (PMID 29615065, 2018).
endometriosis (continued). "Endometriosis has been recognized as a disease accompanied by aberrant methylation and expression of steroidogenic factor-1 (SF-1), estrogen receptor 2 (ESR2), progesterone receptor (PR-B) and HOXA10 genes in the eutopic endometrium of women with endometriosis." (PMID 22233680, 2012). "The combination of the estrogen or progesterone receptor antibody for the nucleus, and the CD10 or COX-2 antibody for the cytoplasm could enhance the accuracy of diagnosis for ectopic endometriosis." (PMID 16961927, 2006). "Metformin treatment of endometriosis has been used, which decreases the expression levels of critical inflammatory and angiogenesis-related genes including VEGF, MMP2, and MMP9, while stimulating tissue inhibitors of metalloproteinase, endometrial stromal cells, and progesterone receptor expression." (PMID 40650261, 2025). "However, reduced PGR expression, or even PR-B promoter hypermethylation in the endometrium is not exclusively confined to patients with endometriosis." (PMID 36830705, 2023). "Compared to controls, macaques with endometriosis exhibited no changes in the expression or localization patterns for PGR and PGRMC1, but exhibited strikingly reduced levels of PGRMC2 transcript and altered intracellular staining patterns for the PGRMC2 protein." (PMID 35406659, 2022). "ii) P4 responses were aberrant in early and late stage endometriosis, and mapping differentially methylated CpG sites with progesterone receptor targets from the literature revealed different but not decreased P4-targets, leading to question the P4-“resistant” phenotype in endometriosis." (PMID 32555663, 2020). "In addition to regulating αv/β3 integrin, HOXA10 regulates FKBP52, a PGR regulator required for implantation and decidualization and reduced in the endometrium of women and non-human primates with endometriosis." (PMID 31387263, 2019). "For medical management, medications used in endometriosis are hormones, including contraceptives, gonadotrophin-releasing hormone agonists/antagonists and selective progesterone receptor modulators, and non-hormonal drugs such as NSAIDS, aromatase inhibitors and danazol." (PMID 30391739, 2018). "Hence, just as endometrial hyperinnervation, or downregulation of PGR, or HOXA10 promoter hypermethylation, CAM-carrying endometria are not exclusively found in women with endometriosis, these aberrations are not sufficient to inevitably cause endometriosis exclusively." (PMID 36830705, 2023). "Progestin and selective progesterone receptor modulators (SPRM) are developed but their efficacy, safety, mechanism and recurrence in endometriosis are not fully studied." (PMID 29615065, 2018).